DDR2 (discoidin domain receptor tyrosine kinase 2)
Diseases named in the same sentence as DDR2 in open-access papers (continued):
Sharing a sentence is not in itself a finding about the gene and the disease.
breast tumor (continued). "In contrast, when WT (DDR2 +ve) breast tumor cells were transplanted into syngeneic Ddr2+/+ or ubiquitous Ddr2-/- hosts there was a decrease in primary tumor volume as well as significantly decreased number of lung metastases." (PMID 31144616, 2019). "We show in mouse breast tumors that the action of the collagen receptor DDR2 in CAFs controls tumor stiffness by reorganizing collagen fibers specifically at the tumor-stromal boundary." (PMID 31144616, 2019). "Deletion of Ddr2 in breast tumor CAFs results in altered collagen fiber organization and decreased lung metastases." (PMID 31144616, 2019). "In vivo, breast tumors deleted of Ddr2 in CAFs or ubiquitously in all cells within tumors exhibit decreased β1 Integrin activation in CAFs, and tumor cells (and CAFs), respectively." (PMID 31144616, 2019). "The action of the fibrillar collagen receptor DDR2 in CAFs, and possibly other cells (see later), within the primary stroma was found to be a critical regulator of breast tumor ECM collagen fiber organization and tumor stiffness." (PMID 31144616, 2019). "In vivo, breast tumors in which Ddr2 is deleted in CAFs are less stiff, have an altered collagen fiber organization particularly at the tumor-stromal boundary, and decreased β1 Integrin activity." (PMID 31144616, 2019). "FSP1cre mediated deletion of Ddr2 in MMTV-PyMT breast tumors resulted in tumors with reduced stiffness, particularly at the tumor-stromal boundary, and significantly altered collagen fiber organization again particularly at the tumor-stromal boundary." (PMID 31144616, 2019). "Since collagen fiber structure and organization within tissues and breast tumor stroma can impact mechanical properties we determined and contrasted the stiffness of WT and Ddr2-/- FSP1cre tumors using Atomic Force Microscopy (AFM)." (PMID 31144616, 2019). "Isolated CAFs from these mouse tumors lack expression of DDR2, as well as human breast tumor CAFs depleted of Ddr2 exhibit decreased mechanotransduction properties." (PMID 31144616, 2019). "Regardless, the accumulated cellular and in vivo data presented herein lend strong support for the mechanotransduction actions of DDR2 in CAFs as likely being a significant contributor to breast tumor mechanical properties (e.g., stiffness)." (PMID 31144616, 2019). "Therefore, our results, in conjunction with other published data, suggest a SNAI1/DDR2 mutual regulation loop that facilitates the sustained activation of the DDR2 signaling pathway in breast tumor metastatic progression." (PMID 36713812, 2022). "Recently, Lin and colleagues revealed that recurrent breast tumors are highly sensitive to ferroptosis, and upregulated expression of DDR2 could promote ferroptosis through the Hippo signaling pathway." (PMID 36457749, 2022). "Moreover, based on the capacity of DDR2 to modulate the TME, we aimed to analyze the relation between DDR2 expression and the recruitment of CAFs and TAMs into the breast tumors." (PMID 35711892, 2022). "In summary, as observed in breast tumor cells, tyrosine kinase-inactive DDR2 (K608E) signaling in CAFs supported paracrine regulation of Matrigel invasion by tumor cells; however, the tyrosine kinase domain of DDR2 (ΔKD) was required." (PMID 34477203, 2021). "In breast tumor cells, DDR2 regulates tumor cell collective invasion by sustaining a SNAIL1 (SNAI1)-mediated epithelial–mesenchymal transition (EMT) invasive program, particularly in keratin 14 (KRT14)-positive leader cells, as well as full activation of collagen-binding integrins." (PMID 34477203, 2021). "In addition to its tumor cell-intrinsic actions, the action of DDR2 in breast tumor stromal CAFs also contributes to lung metastases." (PMID 34477203, 2021). "This is even more important since some breast tumors express DDR2 or both receptors." (PMID 35004699, 2021). "Thus, breast tumor cells expressing tyrosine kinase-inactive K608E.DDR2 exhibited real but diminished lung metastases in vivo." (PMID 34477203, 2021).
breast tumor (continued). "Finally, small-molecule allosteric inhibitors of DDR2 extracellular domain inhibit the tumor–microenvironment interaction and breast tumor invasion." (PMID 32117772, 2020). "To determine if mechanotransduction regulation by DDR2 observed in breast tumor CAFs in ex vivo culture was relevant in an in vivo setting, we deleted the Ddr2 gene in breast tumor CAFs and assessed the mechanical properties of primary tumors and the extent of lung metastasis." (PMID 31144616, 2019). "In addition, Ddr2 expression was depleted in an immortalized human breast tumor CAF cell lines (hCAFs) using shRNA expressing lentiviruses." (PMID 31144616, 2019). "To determine whether the action of DDR2 in metastatic sites was critical, we determined the extent of lung colonization by wild type primary MMTV-PyMT breast tumor cells following tail vein injection of into syngeneic Ddr2+/+ or ubiquitous Ddr2-/- hosts." (PMID 31144616, 2019). "DDR2 was found to be important for the full activation of collagen binding β1-containing Integrins in CAFs in culture and in CAFs and tumor cells within primary breast tumors in vivo." (PMID 31144616, 2019). "It is unclear whether stromal DDR2 has a similar metastatic role in CRC as in breast tumors." (PMID 32117772, 2020). "In recurrent breast tumors, the EMT-driven upregulation of discoidin domain receptor tyrosine kinase 2 (DDR2) maintains growth advantages while also activating YAP/TAZ-mediated ferroptosis susceptibility." (PMID 40075648, 2025). "In this line, we detect DDR2 overexpression in metastatic BC patients with CCND1 gene amplification, a worse survival predictive biomarker in breast tumors." (PMID 35711892, 2022). "As anticipated, in all breast tumor cell lines (human BT549, Hs578 T and MDA-MB-231 cells, as well as mouse 4T1 cells) depletion of DDR2 inhibited Matrigel invasion and, for BT549 and 4T1 cells, migration through 3D collagen I matrices." (PMID 34477203, 2021). "In primary breast tumors of ubiquitous Ddr2-/-; MMTV-PyMT mice the collagen fiber organization surrounding tumor nodules is altered compared with Ddr2+/+; MMTV-PyMT breast tumors." (PMID 31144616, 2019). "Hypoxia is a positive regulator of DDR1 and DDR2 expression in nontumor cells, such as mesenchymal stem cells and smooth muscle cells, and in pituitary adenoma and breast tumor cells." (PMID 33917302, 2021). "Conditioned medium from parental Ddr2+/+ CAFs supported collective migration of breast tumor organoids, whereas medium from Ddr2−/− CAFs did not (quantified in G)." (PMID 34477203, 2021). "The number of CAFs, as defined by PDFGRβ+ve cells, in Ddr2-/- FSP1cre primary breast tumors was not different from WT tumors." (PMID 31144616, 2019). "Western blots of breast tumor CAFs isolated from these mice revealed that DDR2 protein was not expressed." (PMID 31144616, 2019). "Here we show that genetic deletion of the Ddr2 gene in breast tumor CAFs, without altering DDR2 expression in tumor cells, impacts their mechanotransduction properties." (PMID 31144616, 2019). "Normal breast epithelium does not express DDR2, however, in invasive human breast tumor cells DDR2 expression is induced in 50–70% of cases and is significantly correlated with poor outcomes, particularly in aggressive TNBCs." (PMID 31144616, 2019). "The conditioned medium from both parental human BT549 and MDA-MB-231, and mouse 4T1 breast tumor cells enhanced invasion of WT breast tumor cells through Matrigel, and this required the presence of DDR2, as this activity was absent when conditioned medium from DDR2-depleted tumor cells was used." (PMID 34477203, 2021).
squamous cell lung carcinoma (16 papers, 2013 to 2021). A carcinoma arising from squamous bronchial epithelial cells. "In the case of DDR2 mutations in squamous lung cell carcinoma, dasatinib showed particular efficacy." (PMID 27014069, 2016). "In 2011, Hammerman and co-workers have shown that DDR2 is mutated in approximately 4% of lung squamous cell cancer and have reported data to suggest that these mutations induce a gain in DDRs function." (PMID 27014069, 2016). "In GC, DDR2 mutations exist at a rate of 3.7% (8/219; The Cancer Genome Atlas data), which is similar to that observed in lung squamous cell carcinoma." (PMID 26934957, 2016). "DDR1 overexpression is associated with increased cell survival and invasion in hepatocellular carcinomas, pituitary adenoma and prostate cancer, whereas DDR2 is mutated in squamous cell lung cancers and contributes to breast cancer metastasis." (PMID 24768818, 2014). "Dasatinib monotherapy is being studied in advanced squamous cell lung cancers especially in individuals whose tumors harbor mutations in the DDR2 gene." (PMID 23936763, 2013). "Mutations and increased expression of DDR2 have been reported in Hodgkin's Lymphoma and anaplastic large cell lymphoma, lung squamous cell carcinoma, nasopharyngeal carcinoma, sarcoma, hepatocellular carcinoma, aneuploid papillary thyroid cancer and non-small cell lung cancer." (PMID 24505276, 2014). "In addition to lung squamous cell cancers, DDR2 mutations are found in cancers of the kidney, breast, endometrium, colon, and brain." (PMID 23936763, 2013). "Moreover, dasatinib may have potential to treat squamous cell lung cancer in patients harboring oncogenic mutations in DDR2." (PMID 24768818, 2014). "Instead, for lung squamous cell carcinoma, genes such as DDR2, FGFR and genes in the PI3K pathway seem to be more commonly mutated." (PMID 31092229, 2019). "The driver genes involved in lung adenocarcinoma include KRAS, EGFR, ALK, and BRAF, and those implicated in lung squamous cell carcinoma (LSCC) include PIK3CA, FGFR1, EGFR, PDGFRA, and DDR2." (PMID 26373952, 2015). "Furthermore, ponatinib and dasatinib show potent activity against mutant DDR2 in models of squamous cell lung cancer and indeed dasatinib has entered clinical trials for this indication." (PMID 24768818, 2014). "A S768R substitution in DDR2 gene was commonly reported in squamous cell lung carcinoma." (PMID 25173530, 2014). "Moreover, DDR2 (Discoidin domain receptor tyrosine kinase 2) plays an important role in cellular connectivity, survival, migration, and cell proliferation, which contributed to therapeutic target in squamous cell lung cancer." (PMID 34589114, 2021).
hepatocellular carcinoma (10 papers, 2014 to 2024). A malignant tumor that arises from hepatocytes. "In addition, dysregulated methylation or STAT3 activation is also associated with DDR2 expression in gastric cancer, epithelial ovarian cancer, and hepatocellular carcinoma." (PMID 39766183, 2024). "In hepatocellular carcinoma, an association between DDR2 and VEGF has been found." (PMID 33917302, 2021). "For instance, DDR2 expression is upregulated in oxaliplatin-resistant hepatocellular carcinoma cell lines and induces chemoresistance by inducing C-C motif chemokine ligand 20 (CCL20) via STAT3 activation." (PMID 39766183, 2024). "In our present study, we consistently proved that DDR2 knockdown inhibits metastasis of hepatoma cells." (PMID 36471363, 2022). "Our in vitro functional studies suggested that the motility of hepatoma cells was significantly suppressed after silencing the mRNA and protein levels of DDR2." (PMID 36471363, 2022). "Inhibition of DDR2 expression in gastric cancer or hepatocellular carcinoma reduces migration and invasion." (PMID 33917302, 2021). "In hepatocellular carcinoma, invasiveness is assisted by DDR2 through activating ERK2 and stabilizing SNAIL1." (PMID 27793038, 2016). "Mechanismly, CEBPA-DT could bind with hnRNPC and induce the interaction between hnRNPC and DDR2 mRNA, reducing the DDR2 mRNA degradation and further promoting metastasis of hepatoma cells." (PMID 36471363, 2022). "Functionally, wound-healing and transwell assays showed that overexpression of CEBPA-DT could enhance the motility of hepatoma cells, while deletion of DDR2 could block this enhancement." (PMID 36471363, 2022). "Indeed, in hepatocellular carcinoma xenograft, small interfering RNA (siRNA)-mediated inhibition of DDR2 expression in SNU182 cells led to decrease tumor growth." (PMID 33917302, 2021). "Moreover, the western blot experiments verified that CEBPA-DT overexpression repressed the protein expression of E-cadherin and induced the expressions of N-cadherin, Vimentin, Snail and DDR2 in hepatoma cells, while CEBPA-DT down-regulation showed contrary results." (PMID 36471363, 2022). "Similarly, in hepatocellular carcinoma, DDR2 stabilizes Snail1 through ERK2 activity." (PMID 33917302, 2021). "However, the role of DDR2 in hepatocellular carcinoma (HCC) progression and its downstream signaling pathways remain unclear." (PMID 26362312, 2015).
non-small cell lung carcinoma (10 papers, 2007 to 2025). A group of at least three distinct histological types of lung cancer, including non-small cell squamous cell carcinoma, adenocarcinoma, and large cell carcinoma. "Upregulation and mutations (R105S, H136H and N456S) of DDR2 in non-small cell lung cancer and mutations (G531V, S131C, T681I) of DDR2 in squamous cell carcinoma (SCC) of the lung have been reported." (PMID 27793038, 2016). "The somatic mutations in DDR2 gene, reported in non-small cell lung cancer (NSCLC), are involved in up-regulation of cells’ migration, proliferation and survival." (PMID 25173530, 2014). "Although many molecular genetic studies indicate that there are some genetic mutations in non-small cell lung cancer (NSCLC), including EGFR, KRAS, PIK3CA, BRAF, ALK, DDR2, and PDGFRA, only a few studies have focused on the genetic events of salivary gland-type lung carcinomas." (PMID 26575266, 2015). "Tumour samples from 146 non-small cell lung carcinoma (NSCLC) patients were analysed for relative expression of DDR1 and DDR2 using quantitative real-time PCR (qRT-PCR)." (PMID 17299390, 2007). "In conclusion, the genetic mutations associated with PACC are different from those implicated in non-small cell lung cancer, and EGFR, KRAS, BRAF, ALK, PIK3CA, PDGFRA, and DDR2 may not be driver genes in PACC; we must identify other genes for targeted therapy against PACC." (PMID 26373952, 2015).
atherosclerosis (9 papers, 2007 to 2025). A disease characterized by the build-up of fatty material and calcium deposition in the arterial wall resulting in partial or complete occlusion of the arterial lumen. "Ddr2 codes for a transmembrane collagen receptor with tyrosine kinase activity and has been implicated in various disease processes, such as atherosclerosis and cancer." (PMID 31320724, 2019). "Excessive signaling by DDR1 and DDR2 has been linked to the progression of various human diseases, including fibrosis, atherosclerosis and cancer." (PMID 24768818, 2014). "DDR2 has also been linked to the principle of atherosclerosis and lymphanmyomatosis." (PMID 37834343, 2023). "The collagen-binding RTKs, DDR1 and DDR2, have previously been linked to various human diseases including fibrosis, atherosclerosis, and cancer." (PMID 17299390, 2007). "More importantly, for the first time, we have reported that DDR2 is highly expressed in carotid atherosclerotic plaques of human and is distributing around the fatty core of atherosclerosis and overlapping with collagen fibers." (PMID 34956435, 2021). "As a collagen receptor, DDR2 is involved with various diseases such as fibrotic diseases, arthritis, cancer, and atherosclerosis." (PMID 34956435, 2021). "As previous studies have shown that autophagy may mediate AFs activation in atherosclerosis, we also investigated the effect of DDR2 on autophagy." (PMID 40468620, 2025). "Moreover, a crossbred of DDR1−/− and Ldle−/− mice develop atherosclerosis, in which the mice lack the DDR2 gene, long bones become shorter and flat bones become irregular." (PMID 37834343, 2023). "Consequently, we designed this study to elucidate the pathological role of DDR2 in atherosclerosis." (PMID 34956435, 2021). "Discoidin domain receptor 2 (DDR2) takes part in regulation of collagen turnover, mediated by SMCs in development of atherosclerosis." (PMID 24276320, 2013). "Discoidin domain receptor 2 (DDR2): Discoidin domain receptors, DDR1 and DDR2, are tyrosine kinases involved in mammary gland development, long bone growth, and the occurrence of many types of diseases, including arthritis, atherosclerosis, and cancer." (PMID 34834454, 2021).
gastric cancer (9 papers, 2016 to 2026). A primary or metastatic malignant neoplasm involving the stomach. "DDR2 has also previously been implicated as a driver of peritoneal dissemination and its increased expression is associated with unfavourable clinical characteristics in gastric cancer, such as multiple tumour sites and poor prognosis." (PMID 35406381, 2022). "In addition, DDR2 has previously been implicated as a driver of gastric cancer dissemination." (PMID 35406381, 2022). "Therefore, we postulate that the indirect inhibition of AKT3 via DDR2 could be a novel chemopreventative and chemotherapeutic approach for the treatment of E-cadherin-deficient breast and gastric cancers." (PMID 35406381, 2022). "In gastric cancer, DDR2 enhances tumor cell invasiveness and drives EMT by activating mTORC2 and promoting AKT phosphorylation." (PMID 40563472, 2025). "DDR1 and DDR2 were found to be significantly overexpressed in gastric cancer (GC) cell lines compared to normal gastric mucosal cells, particularly in poorly differentiated GC cells." (PMID 37007062, 2023). "In gastric cancer, DDR2 promotes EMT by modulating the mTORC2 (mechanistic target of rapamycin complex 2)/AKT pathway." (PMID 33917302, 2021). "In a xenograft model of gastric cancer, DDR2 overexpression is mediated by demethylation of a DNA promotor and knockdown of DDR2 suppressed peritoneal metastasis." (PMID 27793038, 2016). "In gastric cancer, miR-199b-p promotes tumor stemness and metastasis via the DDR2-mTOR-SOX2 axis." (PMID 40563472, 2025). "In gastric cancer, overexpression of DDR2 promotes tumorigenesis in vivo by inducing tumor growth." (PMID 33917302, 2021).
liver fibrosis (9 papers, 2013 to 2024). "DDR2 was demonstrated to be associated with several pathological processes including hepatic fibrosis, osteoarthritis, wound healing, and tumor metastasis." (PMID 31169440, 2019). "DDR2 inhibition has in fact been associated with enhanced liver fibrosis (evidence generated by the renowned group of prof." (PMID 29859097, 2018). "However, another study reported that the loss of DDR2 promotes hepatic fibrosis after chronic carbon tetrachloride exposure, acting through altered paracrine interactions between hepatic stellate cells and liver-associated macrophages." (PMID 31169440, 2019). "For example, lncRNA XR_877072, a relatively understudied lncRNA, exhibited interactions with multiple mRNAs, including CD74, discoidin domain receptor 2 (DDR2), and tissue inhibitor of metalloproteinase 2 (TIMP2), all of which are closely associated with liver fibrosis." (PMID 38511056, 2024). "The role of DDRs in the fibrosis stage of premalignant liver diseases appears to be complex, especially that of DDR2, which may exert diverse effects on the liver fibrosis stage." (PMID 37007062, 2023). "Knockdown of α5(IV) in CSFC-8B cells significantly reduced DDR2 expression, suggesting α5(IV) may regulate HSC activation and liver fibrosis through DDR2." (PMID 33558482, 2021). "However, DDR2 may play a protective role in chronic and persistent liver fibrosis." (PMID 37007062, 2023). "However, DDR2, HSCs and macrophages may combine to attenuate chronic hepatic fibrosis." (PMID 23409069, 2013). "DDR2 expression induced in liver fibrosis models was detected in activated HSCs but not hepatocytes or Kupffer cells." (PMID 23409069, 2013).